CCND1 (cyclin D1)
Diseases named in the same sentence as CCND1 in open-access papers (continued):
Sharing a sentence is not in itself a finding about the gene and the disease.
lymph node metastasis (continued). "Significant correlations were found between Bcl-2 and deep invasion (p = 0.033), survivin and lymph node metastasis (p = 0.006), as well as cyclin D1 and clinical stage (p = 0.014)." (PMID 25438156, 2014). "The expression of survivin and cyclin D1 significantly correlated with lymph node metastasis and clinical stage (both p<0.05)." (PMID 25438156, 2014). "In the present study, we found that lymph node metastasis with positive lymph node ECS was the major determinant of OSCC outcomes and overexpression of cyclin D1 was significantly associated with lymph node metastasis." (PMID 22336657, 2012). "In our study, after adjusting the tumor differentiation, primary tumor status and lymph node metastasis, cyclin D1 overexpression still adversely influences the patients' survival." (PMID 22336657, 2012). "We then tested the correlation between CCND1 overexpression and clinicopathological features, including tumor size, grade, lymph node metastasis, and patient age." (PMID 22761904, 2012). "We examine a number of factors including clinicopathological features of the primary tumour, lymph node metastasis, and the CCND1 and EGFR gene status of primary tumours, and evaluate the value of predicting the risk of ECS of metastatic lymph nodes." (PMID 21304522, 2011). "We found significantly higher frequency of overexpression of cyclin D1 in patients with advanced age, advanced tumours stage and lymph node metastasis." (PMID 21537090, 2011). "For these studies, cyclin D1 localisation was evaluated in lymph node metastases obtained from three individual patients." (PMID 17375037, 2007). "A significant correlation was also present between cyclin D1 gene amplification and the presence of lymph node metastasis (p = 0.008) as well as between the SI of histone H3, the size of the tumor and the patient's age (p < 0.05, p < 0.001 respectively)." (PMID 15385053, 2004). "Cyclin D1 overexpression is significantly higher in patients with lymph node metastasis (50.0% vs 14.4%, P = 0.002) and with advanced pathological stages (I, 10%; II, 53.8%; IIIa, 41.7%, P = 0.048; stage I vs II, IIIa, P = 0.006)." (PMID 10487623, 1999). "Out of 70 cases, 52 (75%) demonstrated strong and moderate positivity for cyclin D1, and the p-values were 0.017, 0.001, and 0.032 for depth of invasion, TNM stage, and lymph node metastases, respectively, for cyclin D1, which was considered statistically significant." (PMID 37007344, 2023). "A secondary aim was to study CCND1 CN in corresponding axillary lymph node metastases." (PMID 35459982, 2022). "In this study the number of cases with lymph node metastases and CCND1 status may be too low to enable us to draw reliable conclusions." (PMID 35459982, 2022). "In respect to the association of cyclin D1 expression level with the clinico-pathological features of BC, our findings showed that the overexpression of cyclin D1 was associated with IDC, high staging, high grading, lymph node metastasis, and finally hormonal status except HER2-neu status." (PMID 34089425, 2021). "However, a significant positive correlation between cyclin D1 overexpression and lymph node metastasis was found in our study, which was consistent with other studies." (PMID 32697404, 2020). "Cyclin D1 expression was positively correlated with lymph node metastasis (P = .015)." (PMID 32697404, 2020). "Cyclin D1 was positively correlated with lymph node metastasis (P = .015)." (PMID 32697404, 2020). "In conclusion, this study proves that cyclin D1 expression had the strongest correlation with lymph node metastasis and could help to distinguish NPC and non‐NPC patients." (PMID 32697404, 2020). "Finally, three tested clinico-pathological variables (extra thyroidal extension, intraglandular metastasis, and lymph node metastasis) were significant predictors of cyclin D1 immunostaining (P < 0.001)." (PMID 30885146, 2019).
lymph node metastasis (continued). "High DISC1 expression was correlated with smoking status (P=0.049), tumor size (P=0.013), pathology grade (P<0.001), grade (P=0.020), lymph node metastasis (P=0.032), and Ki-67 (P<0.001), p-GSK3β (P<0.001), β-catenin (P<0.001), and Cyclin D1 expression (P<0.001)." (PMID 29029423, 2017). "CCND1 overexpression was significantly associated with lymph node metastasis (p = 0.006), but not with pT, grade, or patient age (p>0.05, respectively)." (PMID 22761904, 2012). "In addition, OSCC survival was significantly influenced by the level of cyclin D1 expression and the relationship still exists in the multivariate analysis after adjusting for age and lymph node metastasis." (PMID 22336657, 2012). "Lymph node metastasis could thus be the pathway that patients with cyclin D1 overexpression had poor prognosis." (PMID 22336657, 2012). "In addition to this, the level of cyclin D1 expression according to lymph node metastasis was statistically significant (P < 0.05)." (PMID 21176227, 2010). "Cox regression analysis revealed that cyclin A overexpression (our definition: SI ≥ 10.5), cyclin D1 overexpression (our definition: SI ≥ 6.1), poorly differentiated histology, lymph node metastasis, TNM stage, tumor size and depth of invasion were all significant prognostic variables for survival." (PMID 15385053, 2004). "Furthermore, CCND1 amplification seems to have great potential as a diagnostic biomarker for lymph node metastasis in a subgroup of clinically nodal negative OSCC although supporting evidence is still not very strong." (PMID 25663615, 2015). "The intersection analysis revealed that three factors, GSDMD, CCND1, and BATF2, were upregulated in postchemotherapy OSCC tumor tissues and highly expressed in tumors from patients with neck lymph node metastasis." (PMID 40178046, 2025). "Lymph node metastasis was predicted by several factors, including a tumor size of 5 mm or larger, sclerosis, S100A4 expression, extrathyroidal invasion, cyclin D1 expression, and multifocality." (PMID 38024552, 2023). "Based on the findings of the present study, it can be concluded that cyclin D1 expression increases with an increase in depth of invasion, TNM stage, and lymph node metastases." (PMID 37007344, 2023). "Lymph node metastasis of 3 (15.8%), 2 (10.5%) and 2 (10.5%) patients exhibited amplifications in all 3 exons of ERBB2, CCND1 and MYC, respectively." (PMID 33298978, 2020). "According to the results, lymph node metastasis (DFS: P = .008; OS: P = .02), tumor stage (DFS: P = .000; OS: P = .000), and cyclin D1 (DFS: P = .038) were powerful independent predictors of NPC patient survival." (PMID 32697404, 2020). "Cyclin D1-positive expression was frequently detected in CRC of stage III, with lymph node metastasis and deeper invasion (P<0.05)." (PMID 25202365, 2014). "Since lymph node metastases have been shown to be an important prognostic factor for DSM, we assessed the additional prognostic value of cyclin D1, FADD and cortactin in late stage LSCC." (PMID 18268491, 2008). "The expression levels of Cyclin D1 and P21 were positively correlated with tumor size and lymph node metastasis (P < 0.05) but not with sex, age, number of tumor lesions, histological subtype, chronic lymphocytic thyroiditis or TNM stage (P < 0.05)." (PMID 37951919, 2023).
lymph node metastasis (continued). "Twelve (92%) out of the 13 MIC cases and 38 (93%) out of the 41 PAC cases were positive for cyclin D1; however, cyclin D1 positivity was not related to extracapsular invasion or lymph node metastasis." (PMID 34563225, 2021). "In each case, only one (2.3%) patient had CNV in all 3 exons of CCND1 and ERBB2 in the corresponding primary tumor and serum, while 2 (4.7%) patients had CNV in all 3 exons of CCND1 in the corresponding primary tumor and lymph node metastasis." (PMID 33298978, 2020). "The cyclin D1 was compared also in patients with lymph node metastasis (N1 or N2) and in patients without lymph node involvement (N0)." (PMID 22024187, 2011). "We show that both cortactin and lymph node metastasis are good predictors for DSM using a multivariate model independent of cyclin D1 and FADD." (PMID 18268491, 2008). "Furthermore, expression of cortactin, cyclin D1 and more recently FADD, have been described separately as potential predictors for increased disease-related mortality, for lymph node metastasis and poor prognosis." (PMID 18268491, 2008). "Secondly, we evaluated whether protein expression of FADD, cyclin D1 and cortactin were related to increased DSM and lymph node metastasis." (PMID 18268491, 2008). "Cox multivariate regression analysis revealed that lymph node metastasis, cyclin A and cyclin D1 overexpression were independent negative prognostic factors after adjustment for the depth of tumor invasion, age and sex of the patient." (PMID 15385053, 2004). "More specifically, tumors with characteristics of lymph node metastasis and lymph node ECS had significantly higher frequency of cyclin D1 overexpression than tumors without those characteristics (p = 0.002)." (PMID 22336657, 2012).
esophageal squamous cell carcinoma (54 papers, 2006 to 2025). Esophageal squamous cell carcinoma (ESCC) is a type of esophageal carcinoma (EC) that can affect any part of the esophagus, but is usually located in the upper or middle third. "This is in line with the positive association between p57KIP2 and cyclin D1 in esophageal squamous cell carcinoma." (PMID 23580324, 2013). "In this study, we investigated the expression pattern of β-catenin and cyclin D1 using immunohistochemistry and searched for mutations in exon 3 of the β-catenin gene and Axin gene in esophageal squamous cell carcinoma." (PMID 17309796, 2007). "MACC1, c-Met, and cyclin D1 proteins are closely related to the occurrence and development of esophageal squamous cell carcinoma." (PMID 35242498, 2022). "The positive expression rate of cyclin D1 in esophageal squamous cell carcinoma patients was 41.8% (72/172)." (PMID 35242498, 2022). "Dual inhibition of the PI3K/AKT/mTOR pathway with MK2206 and BEZ235 caused cell cycle arrest and enhanced apoptosis through the downstream effectors SKP2, MCL-1, and cyclin D1 in esophageal squamous cell carcinoma cells." (PMID 33659215, 2020). "The dysregulation of Fbxo4-cyclin D1 axis occurs at high frequency in esophageal squamous cell carcinoma (ESCC), where it promotes ESCC development and progression." (PMID 30899002, 2019). "The Epstein–Barr virus ED-L2, an early lytic cycle promoter that targets the cyclin D1 in a transgenic mouse model leading to dysplasia and premalignant condition in the esophagus is the most commonly used method to induce esophageal squamous cell carcinoma." (PMID 27956773, 2016). "In this paper, we investigated the expression pattern of β-catenin and cyclin D1 in esophageal squamous cell carcinoma." (PMID 17309796, 2007). "A fraction of esophageal squamous cell carcinomas have abnormal nuclear accumulation of β-catenin accompanied with increased cyclin D1 expression." (PMID 17309796, 2007). "Furthermore, studies have demonstrated that combination therapies can overcome resistance to the cyclin-dependent kinase 4/6 (CDK4/6) inhibitor palbociclib in esophageal squamous cell carcinoma (ESCC) with dysregulation of the FBXO4-cyclin D1 axis." (PMID 40534867, 2025). "In addition, the positive association between cyclin D1 expression and tumor progression has been validated in different cancers, including lung adenocarcinoma, head and neck squamous cell carcinoma, and esophageal squamous cell carcinoma (ESCC)." (PMID 37427143, 2023). "MACC1 may affect the prognosis of patients with esophageal squamous cell carcinoma by regulating the expression of the c-Met/cyclin D1 axis." (PMID 35242498, 2022). "miR-503 (targeting CCND1) can be used as a tumor suppressor for esophageal squamous cell carcinoma." (PMID 36078046, 2022). "A subset of esophageal squamous cell carcinoma harbors dysregulated Fbxo4- cyclin D1 axis." (PMID 30899002, 2019). "Additionally, miR-195 reduces the phosphorylation levels of ERK1/2 and suppresses the expression of cyclin D1 in cell lines derived from esophageal squamous cell cancer." (PMID 29596304, 2018). "The lncRNA HOX transcript antisense RNA (HOTAIR) can sponge miR-1 and upregulate cyclin D1 (CCND1) expression, thus facilitating the tumorigenesis of esophageal squamous cell carcinoma (ESCC)." (PMID 35704638, 2022). "The purpose of this study was to analyze the expression of MACC1, c-Met, and cyclin D1 in esophageal squamous cell carcinoma and their relationship with clinicopathological parameters and to initially clarify the mechanism of action of the three in esophageal squamous cell carcinoma." (PMID 35242498, 2022).
esophageal squamous cell carcinoma (continued). "We aimed to develop a new biomarker to predict cyclin D1 (CCND1) status using plasma DNA in oesophageal squamous cell carcinoma (ESCC) patients." (PMID 20389301, 2010). "The same effect was described on esophageal squamous cell carcinomas (ESCC cells), metformin-induced AMPK activation and p-mTOR, S6K1 and cyclin D1 inhibition." (PMID 35327549, 2022). "This study aimed to explore the relationships between the sex-determining region on Y (SRY) box transcription factor 17 (SOX17), Cyclin D1, vascular endothelial cadherin (VE-cadherin), and vasculogenic mimicry (VM) in the occurrence and development of esophageal squamous cell carcinoma (ESCC)." (PMID 36072972, 2022). "Located on 11q13, a frequently mutated area in esophageal squamous cancer, and nearby Cyclin D1, CCND1, which is overexpressed in esophageal adenocarcinoma, CPT1A has been identified as a marker for poor survival in esophageal squamous cell carcinoma." (PMID 36233047, 2022). "In this study we found ATO treatment induced increased ROS production and DNA damage in esophageal squamous cell carcinoma (ESCC) cells, led to DNA damage mediated degradation of Cyclin D1 and upregulation of PD-L1 in these cancer cells." (PMID 33046973, 2020). "A clustered abnormality in copy number was observed in several genes, including CCND1 and SOX2 and/or TP63, in esophageal SCC, whereas a more widespread genomic instability and total DNA copy number alterations were observed in esophageal ADC." (PMID 33748520, 2018). "Additionally, a study found that miR-1 can impede the growth of esophageal squamous cell carcinoma by downregulating the expression of MET, CDK4, and cyclin D1." (PMID 38504949, 2024). "Overexpression of Cyclin D1 (CCND1) has been reported as an early event in oral and esophageal SCC." (PMID 37474617, 2023). "The purpose of this study was to preliminarily analyze the expressions of MACC1, c-Met, and cyclin D1 in esophageal squamous cell carcinoma and their relationship with clinicopathological parameters, as well as the effects of the expressions of the three proteins on the prognosis of ESCC." (PMID 35242498, 2022). "Moreover, depletion of S6 results in a sharp decrease of cyclin D1 and CDK2 levels to regulate cell viability in esophageal squamous cell carcinoma." (PMID 28212559, 2017). "While previous work in fibroblasts suggested that forced expression of E2F8 reduced cell proliferation through a negative feedback loop, additional research in esophageal squamous cell carcinoma identified E2F8 as a promoter of proliferation through CCND1/p21 signaling." (PMID 38086808, 2023). "Through AKT signaling, RAP1A promotes metastasis in esophageal squamous cell carcinoma (ESCC), and an aggressive phenotype in colorectal cancer through PTEN/FOXO3/CCND1 pathway." (PMID 33958005, 2021). "Decreased APC increases β-catenin, cyclin D1, c-Myc, and PKM2 expression, resulting in mouse aerobic glycolysis, cell proliferation, and enhanced esophageal squamous cell carcinoma (ESCC) formation." (PMID 35087575, 2021). "Additionally, Ding and colleagues reported that upregulation of miR-29c downregulated cyclin E and suppressed its oncogenic activity in esophageal squamous cell carcinoma, without affecting other G1 phase-related proteins level, such as cyclin D1, cyclin D2." (PMID 23383003, 2013).